ANKRD20A1 (ankyrin repeat domain 20 family member A1)
Synonyms: ANKRD20A; DKFZp434A171
Tractability: Antibody: its Gene Ontology location is reachable by antibodies, with medium confidence. PROTAC: ubiquitination databases record sites on it.
Gene: Protein-coding gene on chromosome 9 (67,832,765 to 67,920,552, forward strand). Ensembl gene ENSG00000260691.
Subcellular location (Human Protein Atlas): Nucleoplasm
Gene Ontology:
Cellular component: plasma membrane
Genetic constraint (gnomAD): Loss-of-function variants: 1 observed, 9.27 expected, observed/expected ratio (o/e) 0.11, 90% interval 0.037 to 0.51. That is too few expected variants to judge how well the gene tolerates losing a copy. Missense variants: 14 observed, 97.37 expected, observed/expected ratio (o/e) 0.14, 90% interval 0.094 to 0.22. Synonymous variants: 5 observed, 30.51 expected, observed/expected ratio (o/e) 0.16, 90% interval 0.085 to 0.34.
Homologues: Orthologues: tropical clawed frog ankrd7 (18% identical), zebrafish si:ch211-272n13.3 (12% identical), Caenorhabditis elegans lem-3 (10% identical), Drosophila melanogaster CG8679 (9% identical), Caenorhabditis elegans F44E5.15 (4% identical), Drosophila melanogaster CG42391 (2% identical), Caenorhabditis elegans K07D4.2 (1% identical). Paralogues in human: ANKRD26 (45% identical), ANKRD18B (43% identical), ANKRD18A (42% identical), ANKRD30A (37% identical), ANKRD30B (36% identical), ANKRD62 (34% identical), ANKRD30BL (13% identical).
Diseases named in the same sentence as ANKRD20A1 in open-access papers:
ANKRD20A1 is named in the same sentence as 2 diseases in open-access papers, as found by Europe PMC text mining. Sharing a sentence is not in itself a finding about the gene and the disease. The quoted sentences say what the papers report.
dilated cardiomyopathy (1 paper, 2025). Cardiomyopathy which is characterized by dilation and contractile dysfunction of the left and right ventricles. "TRAT1 was involved in ribosome biogenesis and cardiac-related pathways such as dilated cardiomyopathy, whereas ANKRD20A1 was associated with gene replication and cell cycle-related processes, highlighting its potential role in transcriptional regulation in HCM." (PMID 41200169, 2025).
systemic lupus erythematosus (1 paper, 2025). An autoimmune multi-organ disease typically associated with vasculopathy and autoantibody production. "TRAT1 shared several overlapping pathways with SYDE2, while ANKRD20A1 primarily affected DNA replication, transcription factor activity, and systemic lupus erythematosus-related processes." (PMID 41200169, 2025).